ZNF268 (zinc finger protein 268)
Description:
[Isoform 1]: Acts as a transcriptional repressor. Inhibits erythroid differentiation and tumor cell proliferation. Plays a role during ovarian cancer development and progression. [Isoform 2]: Contributes to cervical carcinogenesis in part through the TNF-induced NF-kappa-B signaling pathway by interacting with the I-kappa-B-kinase (IKK) core complex. Involved in the regulation of antiviral interferon signaling. During viral infection, recruits SETD4 to TBK1, leading to TBK1 monomethylation, which is critical for the assembly of TBK1 complex and IRF3 signaling.
Synonyms: HZF3
Tractability: PROTAC: ubiquitination databases record sites on it.
Gene: Protein-coding gene on chromosome 12 (133,181,409 to 133,214,832, forward strand). Ensembl gene ENSG00000090612.
Subcellular location: Nucleus (Isoform 1); Nucleus (Isoform 2); Cytoplasm
Subcellular location (Human Protein Atlas): Cytosol
Pathways (Reactome):
Gene expression (Transcription): Generic Transcription Pathway
Gene Ontology:
Molecular function: DNA binding; DNA-binding transcription factor activity; transcription cis-regulatory region binding
Biological process: negative regulation of apoptotic process; negative regulation of cell population proliferation; negative regulation of transcription by RNA polymerase II; positive regulation of apoptotic process; positive regulation of cell differentiation; positive regulation of cell migration; positive regulation of cell population proliferation; positive regulation of transcription by RNA polymerase II; regulation of cell cycle; regulation of mitotic cell cycle; regulation of DNA-templated transcription; regulation of protein catabolic process
Cellular component: cytoplasm; nucleus
Genetic constraint (gnomAD): Loss-of-function variants: 25 observed, 24.74 expected, observed/expected ratio (o/e) 1.01, 90% interval 0.74 to 1.41. The synonymous counts are far from expectation, so gnomAD's model fits this gene poorly and the ratio says little. Missense variants: 1,240 observed, 1,025.5 expected, observed/expected ratio (o/e) 1.21, 90% interval 1.15 to 1.27. Synonymous variants: 429 observed, 343.64 expected, observed/expected ratio (o/e) 1.25, 90% interval 1.15 to 1.35.
Homologues: Orthologues: chimpanzee ZNF268 (99% identical), macaque ZNF268 (95% identical), pig ZNF268 (82% identical), dog ZNF268 (82% identical). Paralogues in human: ZNF615 (33% identical), ZNF432 (32% identical), RBAK (27% identical), ZNF182 (24% identical), ZNF605 (24% identical), ZNF33B (24% identical), ZNF484 (24% identical), ZNF717 (24% identical), ZNF41 (23% identical), ZNF658 (23% identical), ZNF26 (23% identical), ZNF33A (23% identical), and 164 more.
Diseases named in the same sentence as ZNF268 in open-access papers:
ZNF268 is named in the same sentence as 9 diseases in open-access papers, as found by Europe PMC text mining. Sharing a sentence is not in itself a finding about the gene and the disease. The quoted sentences say what the papers report.
ovarian carcinoma (4 papers, 2013 to 2021). A malignant neoplasm originating from the surface ovarian epithelium. "The high expression levels of ZNF268 in human ovarian carcinomas may be associated with the ability of ZNF268 to promote cell migration." (PMID 23946776, 2013). "The present study revealed several significant roles for ZNF268 in human ovarian cancer development and progression." (PMID 23946776, 2013). "ZNF268-knockdown increased the viability, colony formation and growth of in vivo xenografts of ovarian carcinoma SKOV-3 cells, whereas SKOV-3 cell migration was inhibited." (PMID 23946776, 2013). "The present study used immunostaining, western blotting and quantitative real-time PCR to demonstrate that ZNF268 is overexpressed in human ovarian carcinomas." (PMID 23946776, 2013). "The results obtained from the current study are likely to provide an improved understanding of the molecular mechanisms underlying ovarian cancer progression and demonstrate the potential of ZNF268 as a novel therapeutic target for ovarian cancer." (PMID 23946776, 2013). "Second, ZNF268-knockdown was demonstrated to affect biological functions, including the proliferation and migration of ovarian cancer SKOV-3 cells." (PMID 23946776, 2013). "ZNF268 was overexpressed in the majority of the ovarian cancer tissues (∼84%), while ZNF268 expression was rarely detected in the normal tissues." (PMID 23946776, 2013). "We previously observed different expression patterns of ZNF268 in normal human ovarian tissues compared with ovarian cancer tissues using the tissue microarray method." (PMID 23946776, 2013). "Opposing effects upon ZNF268 knockdown were observed in ovarian cancer." (PMID 33672287, 2021). "The inhibitory effect on cancer cell proliferation and concomitant stimulation of migratory potential in ovarian cancer is somewhat confounding in the view of potential oncogenic properties; thus, further studies are needed for an improved understanding of ZNF268 functioning in cancer." (PMID 33672287, 2021). "ZNF268 is predicted to be a high affinity target of miR-1260b, with a target score of 100 (the maximum of target score) in the miRDB database, and is found to be overexpressed in cervical cancer and ovarian carcinomas." (PMID 34805186, 2021). "Using an immunohistochemistry assay with anti-SD that recognizes the ZNF268a and ZNF268b2 isoforms the present results demonstrated that total ZNF268 protein was overexpressed in ovarian cancer and that ZNF268 (ZNF268a/ZNF268b2)-knockdown increases the growth of SKOV-3 cells." (PMID 23946776, 2013). "First, it was observed that ZNF268 is overexpressed in ovarian carcinomas." (PMID 23946776, 2013). "From this perspective, ZNF268-knockdown suppresses SKOV-3 migration, indicating that ZNF268 may serve as a potential therapeutic target for ovarian cancer." (PMID 23946776, 2013). "Therefore, the inhibitory function of ZNF268 on cell proliferation may appear controversial due to its high expression levels in ovarian carcinomas." (PMID 23946776, 2013). "The present study demonstrated that ZNF268 was overexpressed in human ovarian cancer tissues and that ZNF268-knockdown increased the proliferation, while simultaneously decreasing the migration, of SKOV-3 ovarian cancer cells." (PMID 23946776, 2013). "The results indicate that ZNF268-knockdown may increase the growth rate of SKOV-3 cells by promoting cell cycle progression, suggesting that ZNF268 may inhibit ovarian cancer cell growth in humans." (PMID 23946776, 2013).
cervical cancer (2 papers, 2013 to 2021). A primary or metastatic malignant neoplasm involving the cervix. "This hypothesis is supported by findings indicating that ZNF268-knockdown promotes the proliferation of erythroleukemia K562 cells, while inhibiting the growth of cervical cancer HeLa cells." (PMID 23946776, 2013). "Previous studies have suggested that ZNF268 may be involved in human foetal liver development, haematological diseases and cervical cancer development." (PMID 23946776, 2013).
chronic myelogenous leukemia (1 paper, 2012). "Here, we investigated the mechanism underlying decreased expression of ZNF268 as well as the consequences of ZNF268 downregulation in K562 cells, a human erythroleukemia cell line derived from a patient with chronic myelogenous leukemia." (PMID 22235304, 2012).
leukemia (1 paper, 2018). A malignant (clonal) hematologic disorder, involving hematopoietic stem cells and characterized by the presence of primitive or atypical myeloid or lymphoid cells in the bone marrow and the blood. "Disorders in ZNF268 expression and processing may cause cancer and leukemia, but not all functions of ZNF268 are yet known." (PMID 29928572, 2018).
cancer (3 papers, 2018 to 2022). A tumor composed of atypical neoplastic, often pleomorphic cells that invade other tissues. "The negatively co-relationship between ZNF268 expression and NK bright cells infiltration can contribute to the anti-cancer function." (PMID 35735115, 2022). "And the Treg cells infiltration can be inhibited by ZNF268 expression, which also enhancing the anti-cancer performances." (PMID 35735115, 2022). "First, we investigated the expression of ZNF268 in 33 types of human cancer." (PMID 35735115, 2022). "ZNF268, another KRAB-ZFP with oncogene and TSG potential, was found upregulated in cervical and ovarian cancers." (PMID 33672287, 2021).
tumor (3 papers, 2012 to 2022). "ZNF268 acts as a tumor suppressor, and it is associated with apoptosis and immune cell infiltration in ccRCC." (PMID 35735115, 2022). "Accumulating evidence proves that zinc finger protein 268 (ZNF268) is associated with tumor progression, but the detailed regulatory functions of ZNF268 in ccRCC require further exploration." (PMID 35735115, 2022). "Nevertheless, the relationship regarding the relevance of ZNF268 expression, prognosis, and tumor immune infiltration in ccRCC remains undetermined." (PMID 35735115, 2022). "Our study reveals that ZNF268 overexpression effectively inhibits cell proliferation, migration, and invasion in vitro, and the results from the xenograft tumor model further confirm the tumor-suppressing performance of ZNF268." (PMID 35735115, 2022). "Collectively, this work proves that ZNF268 functions as a considerable inhibitor of tumor prognosis and has promising prospects in ccRCC therapy." (PMID 35735115, 2022). "The ZNF268 anti-tumor function was investigated in this study for the potential clinical application of ccRCC therapy." (PMID 35735115, 2022). "Based on the experiments both in vitro and in vivo, it was exhibited that ZNF268 overexpression effectively suppressed proliferation, migration, and invasion of Caki-1 cells, and inhibited tumor progression." (PMID 35735115, 2022). "In summary, this work revealed that AC093157.1/miR-27a-3p/ZNF268 axis promoting cell apoptosis and immune cell tumor infiltration for tumor inhibition in ccRCC." (PMID 35735115, 2022). "Caki-1/oe-ZNF268 cells were injected in the flank of NOD-SCID mice, and tumor volume was recorded every three days with the lower proliferation curve of OE-ZNF268 indicating the effective anti-tumor performances." (PMID 35735115, 2022). "To explore the potential mechanism of anti-tumor function in vivo, we further analyzed the relationships between ZNF268 expression and immune cell infiltration in ccRCC." (PMID 35735115, 2022). "The results from tumor weight evidenced that overexpression of ZNF268 inhibited tumor growth in vivo." (PMID 35735115, 2022). "In this study, we analyzed the expression and function of ZNF268 in ccRCC and verified the regulatory effect of ZNF268 on tumor progression both in vitro and in vivo." (PMID 35735115, 2022). "TCGA and GTEx databases proved the potential tumor-suppressing function, which was measured both in vitro and in vivo after ZNF268 over-expression." (PMID 35735115, 2022). "The potential mechanisms of ZNF268 anti-tumor function originated from the enhanced cell apoptosis, which had been confirmed by various experiments." (PMID 35735115, 2022). "All the evidences from both in vitro and in silico analysis confirmed that AC093157.1/miR-27a-3p axis was considered as the upstream ncRNA which regulating ZNF268 expression and tumor progression." (PMID 35735115, 2022). "Subsequently, tumor-infiltrating immune cells, as well as upstream noncoding RNAs (ncRNAs) related to the tumor-suppressing function of ZNF268, were identified by in silico analyses." (PMID 35735115, 2022). "This study revealed ncRNA mediated ZNF268 functioned well as the tumor suppressor by promoting cell apoptosis and immune cell tumor infiltration in ccRCC." (PMID 35735115, 2022). "Simultaneous, the representative images of xenograft tumors among the two subgroups also proved that ZNF268 functioned as a tumor suppressor in ccRCC." (PMID 35735115, 2022). "Mice received a subcutaneous injection of ZNF268-silenced clones (n = 5) or vector control clones (n = 5) in the right flank, so that tumor comparisons would be controlled for each individual mouse." (PMID 22235304, 2012). "LncRNA-AC093157.1 functions as the predicted upstream lncRNA of miR-27a-3p/ZNF268 has been considered an oncogene in ccRCC for the negative association with tumor prognosis, which is also proved by results of experiments in vitro." (PMID 35735115, 2022).
tumor (continued). "Additionally, the IHC results of tumors proved the upregulation of ZNF268 in vivo, providing evidence of a potential tumor-suppressing effect." (PMID 35735115, 2022). "We next explored ZNF268 function in vivo using a xenograft tumor model." (PMID 35735115, 2022). "In addition, ZNF268 expression was negatively correlated with tumor progression and positively correlated with overall and disease-specific survival." (PMID 35735115, 2022). "All clinical and experimental evidence indicates that ZNF268 could be considered a tumor suppressor for ccRCC patients." (PMID 35735115, 2022). "The level of ZNF268 was positively related to the immune cell infiltration in the tumor." (PMID 35735115, 2022). "The results from in vitro experiments revealed a potential tumor-suppressing function of ZNF268." (PMID 35735115, 2022). "Furthermore, ZNF268 knockdown impeded tumor growth and increased the expression of apoptosis markers in a nude mouse model." (PMID 33672287, 2021). "We found that ZNF268 silencing promoted subcutaneous tumor growth in nude mice." (PMID 22235304, 2012). "The results indicate that ZNF268 is positively related to TCM and T helper cells infiltration, suggesting a tumor-suppressing effect." (PMID 35735115, 2022). "Meanwhile, elevated ZNF268 expression activated the TCM and T helper cells infiltration, inhibited the infiltration of Treg in ccRCC, which assisting in suppressing the tumor progress." (PMID 35735115, 2022). "ZNF268 may be similar to Egr1, which has been identified as a target of GATA-1 by ChIP-seq analysis and is regarded as a tumor repressor." (PMID 22235304, 2012).
hematological malignancies (1 paper, 2022). "ZNF268 was described as chronic lymphocytic leukemia (CLL)-associated antigen, its aberrant alternative splicing was detected in human hematological malignancies." (PMID 36275462, 2022).
ZNF268 also shares sentences with these, for which no sentence is quoted: clear cell renal cell carcinoma (1 paper); erythroleukemia (1).